FGF21 (fibroblast growth factor 21)
Diseases named in the same sentence as FGF21 in open-access papers (continued):
Sharing a sentence is not in itself a finding about the gene and the disease.
Obesity (continued). "Circulating FGF21 concentration is known to be increased in obesity and type 2 diabetes." (PMID 37094639, 2023). "However, FGF21 levels are elevated in obese patients and are further increased in obese patients with T2D, so obesity is proposed to be a FGF21‐resistant state." (PMID 37442561, 2023). "Thus, FGF21 and its analogs have been identified as potentially effective therapeutic drugs for conditions like type 2 diabetes, obesity, and NAFLD." (PMID 38116563, 2023). "Furthermore, long-term production of FGF21 via administration of AAV8-pAAT-FGF21 targeting the liver reversed the hallmarks of obesity and T2D in high-fat diet-fed mice." (PMID 37755259, 2023). "They concluded that human FGF-21 resistance in T2DM and obesity could result from increases in FGF-21-resistant ectopic fat accumulation." (PMID 37436597, 2023). "Further, the parallel increase in circulating FGF21 and GCs levels was also observed in obese objects, including both rodents and humans, revealing that FGF21 may also play a key role in the development of obesity." (PMID 37834368, 2023). "One explanation might be, that the expression of KLB and FGF-21 receptor 1 and 3 in the liver is increased in patients with obesity, which might result in an increased responsiveness to exogenous FGF-21." (PMID 37239098, 2023). "Therefore, the contribution of KLB is associated with increased sensitivity to the beneficial effects of FGF21 on obesity and type 2 diabetes, including regulation of body weight, plasma lipid levels and insulin sensitivity." (PMID 37019912, 2023). "Circulating FGF-21 levels were positively correlated with obesity-related metabolic complications, renal function, atherosclerosis, and hypertension, indicating that FGF-21 may be used as a biomarker in metabolic or even non-metabolic diseases." (PMID 36238554, 2022). "In accordance with irisin levels, serum FGF-21 concentrations are higher in obesity, reduced in anorexia nervosa and related to body FM, suggesting that FGF-21 levels may reflect energy stores." (PMID 36556065, 2022). "Fibroblast growth factor 21 (FGF21) is an obesity- and temperature-related hormone that upregulates the expression of RBM3, which is beneficial as a recombinant treatment and has been tested under different experimental pathological conditions, including stroke." (PMID 35207221, 2022). "Conversely, using genetic or pharmacological modulation, FGF21 displays cardioprotective properties under dysregulated glucose and lipid metabolism FGF21 also promotes lipophagy in mouse cardiomyocytes in obesity-related cardiomyopathy by preventing lipid accumulation." (PMID 35983184, 2022). "This reproduces a clinical scenario where patients suffering from obesity induced liver disease receive a treatment with a FGF21 analogue and might wish to conceive later." (PMID 36406708, 2022). "Collectively, these data suggest that FGF21 could protect the body against obesity and insulin resistance." (PMID 36359757, 2022). "Subsequently, it has also been discovered that circulating FGF21 levels were associated with obesity but not with PCOS." (PMID 35574015, 2022). "Furthermore, the overexpression of KLB in adipose tissue is sufficient to enhance FGF21 responses and to combat dietary obesity in mice." (PMID 36034414, 2022). "In mice, FGF21 administration has been shown to increase fatty acid oxidation and lower blood glucose as well as triglyceride levels protecting animals from diet induced obesity and diabetes." (PMID 35743140, 2022). "The hepatokine FGF21 has a potential therapeutic effect in the treatment of obesity." (PMID 35232994, 2022). "Thus, targeting Mat1a activates the liver-BAT axis by increasing NRF2-mediated FGF21 secretion, which prevents obesity, insulin resistance and hepatosteatosis." (PMID 35232994, 2022). "However, the serum FGF21 level reduced after 36 and 12 weeks of exercise in humans and animals with obesity." (PMID 36006939, 2022).
Obesity (continued). "The well-established biological functions of FGF21 as a key regulator of energy balance, glucose homeostasis, fat metabolism and insulin sensitivity provide clues as to the SLC6A19 loss-associated protection against obesity and metabolic syndrome." (PMID 35204736, 2022). "Overall, in addition to its metabolic effects, FGF21 could also act as an anti-inflammatory factor for the treatment of obesity-induced metabolic dysfunctions." (PMID 35909571, 2022). "•GDF15 and FGF21 synergistically protect against obesity-induced hepatosteatosis." (PMID 36064109, 2022). "FGF21 may be elevated, although this prediction is complicated by the possible differing roles of FGF21 in rodent models and humans, and by the suggestion of FGF21 resistance in humans with obesity." (PMID 35629964, 2022). "GDF15 and FGF21 have been found to be associated with a range of non-mitochondrial diseases, including cancer, obesity, renal diseases, diabetes, liver diseases, and non-mitochondrial myopathies." (PMID 35498801, 2022). "Moreover, elevated FGF21 levels that correlates with obesity, have been attributed to the establishment of an adaptive mechanism for the mitigation of insulin resistance and its metabolic consequences." (PMID 34822062, 2022). "High vs low dietary sugar intake was associated with greater FGF21 responses to acute sucrose ingestion in healthy-weight individuals (ß=8.51, p=0.04), but not individuals with overweight or obesity (p>0.05)." (PMID 35491674, 2022). "And during past decades, the beneficial effect of FGF21 analogs and FGF21-receptor agonists confirmed by preclinical and clinical experiments has indicated that FGF21 is an attractive target for the treatment of metabolic diseases, particularly for obesity, T2DM, and NASH." (PMID 36618930, 2022). "FGF21 is supposed to have therapeutic potential for the treatment of metabolic syndrome and obesity, as it increases glucose uptake by the muscles and adipose tissue (AT), induces adiponectin secretion by AT and increases energy expenditure due to induction of browning of white adipose tissue (WAT)." (PMID 36235821, 2022). "Therefore, the cFGF21 level beyond 3 hours postexercise would mainly be associated with the healthy benefits of exercise, including reduced obesity and liver fat content, decreased obesity-induced FGF21 resistance, and improved glucose and lipid metabolism." (PMID 36093108, 2022). "In addition, overexpression of FGF-21 prevents age-related weight gain, and this study underscores the potential of FGF-21 gene therapy for the treatment of obesity." (PMID 35250869, 2022). "It leads to the conclusion that both mechanisms can be involved and increased FGF21 serum levels in obesity related comorbidities may be a concert of compensatory increased secretion and receptor resistance." (PMID 35909532, 2022). "As FGF21 treatment in animal obesity models resulted in reduction of adiposity, improved insulin sensitivity, a decrease of cholesterol and triglyceride levels, FGF21 was suggested to have potential as a novel therapy for obesity and related diseases like T2D and PCOS." (PMID 36289764, 2022). "In addition, FGF21 plays a key role in hypothalamic inflammation, and the decrease in FGF21 levels induces obesity-related hypothalamic inflammation." (PMID 35909571, 2022). "To date, the underlying mechanisms how FGF21 counteracts obesity are not understood but associate with the browning of WAT." (PMID 36034414, 2022). "Moreover, both recombinant FGF21 and FGF21 analogs have emerged as promising therapeutic drug candidates for metabolic disorders, including hepatic steatosis, obesity, insulin resistance and dyslipidemia, in several animal studies." (PMID 36012166, 2022). "This might be due to FGF21 resistance, and also suggests that the dysfunctional FGF21-adiponectin axis contributes to the pathogenesis of obesity-related metabolic syndrome." (PMID 36618930, 2022).
Obesity (continued). "It is suggested that the increased levels of FGF-21 in individuals with obesity-related metabolic dysfunction could be a physiologic response to counterbalance metabolic stress." (PMID 35147910, 2022). "Thus, in patients with type II diabetes or obesity, plasma concentrations of FGF21 are significantly increased compared to control healthy subjects." (PMID 35282437, 2022). "Indeed, animal studies have been able to show that a reduction of obesity-induced metabolic disturbances via enhancing FGF21 sensitivity in adipose tissue is possible, e.g., by exercise." (PMID 36235821, 2022). "On the other hand, Enoxacin (another quinolone) induced intrinsic oxidative metabolism in a beneficial way, which resulted in enhanced TCA cycle, downregulation of mir-34a-5p and increased FGF21 signals, and eventually increased beige adipogenesis and ameliorated obesity." (PMID 35154482, 2022). "Thus, further investigations are required to understand and identify the pathways of dysregulated FGF21 signalling in obesity, which at the end will be important for the clinical translation of FGF21-based therapies." (PMID 36034414, 2022). "Thus, preclinical and clinical evidence corroborate that FGF21 is a promising candidate to combat obesity related diseases." (PMID 36034414, 2022). "Indeed, hepatic transcription of fgf21 gene in mice is triggered by endoplasmic reticulum and oxidative stress resulting from obesity and NAFLD as a compensatory reaction." (PMID 35909532, 2022). "Thus, overall, FGF21 is an insulin-stimulated beneficial myokine that regulates energy metabolism and protects against chronic metabolic disorders such as T2D and obesity." (PMID 35563026, 2022). "Serum FGF21 levels were similar between young Sirt7 KO and control mice, but we demonstrated previously that young Sirt7 KO mice show resistance to high-fat diet-induced obesity, glucose intolerance, and fatty liver." (PMID 36429037, 2022). "Likewise, obesity and diabetic patients who received human recombinant FGF21 for 4 weeks demonstrated improved level of HDL-C." (PMID 36474191, 2022). "However, circulating FGF21 levels are increased whereas plasma adiponectin concentrations are reduced in both animals and humans with obesity." (PMID 36618930, 2022). "Here we review the actions of FGF21 and summarize the associated clinical trials in obesity, type 2 diabetes mellitus (T2DM), and NAFLD, to help understand and promote the development of efficient treatment for metabolic diseases via targeting FGF21." (PMID 36618930, 2022). "Recently, the new proteins of the same family members, fibroblast growth factor-19 (FGF-19) and fibroblast growth factor-21 (FGF-21), with pleiotropic effects on development, organogenesis and metabolism have been proposed to be involved in the pathogenesis of obesity." (PMID 36362225, 2022). "Studies showed a significant decrease in obesity in monkeys and mice upon FGF21 treatment." (PMID 36699319, 2022). "Although the potential therapeutic relevance of modulating the expression/activity of AHSG, ANGPTL4, LECT2 and FGF21 for treating obesity, IR and liver metabolic disorders is still unclear, targeting these hepatokines appears to be a promising strategy in addition to other currently used therapies." (PMID 35409319, 2022). "Obesity, often associated with non-alcoholic fatty liver disease (NAFLD), is characterized by an imbalance between energy expenditure and food intake, which is also reflected by desensitization of fibroblast growth factor 21 (FGF21)." (PMID 36034917, 2022). "However, elevated levels of FGF-21 are reported in individuals with type 2 diabetes, obesity, and cardiovascular disease, and FGF-21 is therefore suggested as a biomarker of these conditions." (PMID 35147910, 2022). "Indeed, one of the hepatokines, fibroblast growth factor 21 (FGF21), is considered a biomarker of obesity, T2DM and NAFLD." (PMID 35740032, 2022).
Obesity (continued). "In an animal experiment, the administration of BMP9 into obese mice expresses enhanced gene expression of fibroblast growth factor 21 (FGF21), which is a metabolic regulator, and reduced a spectrum of pathological symptoms caused by high-fat diet- (HFD-) induced obesity." (PMID 34258293, 2021). "Since FGF21 show a strong association with obesity, we categorized the study participants into non-obese (BMI < 25 kg/m2) and obese (BMI ≥ 25 kg/m2) groups and assessed the association between FGF21 levels and each parameter in both groups." (PMID 34799626, 2021). "It stimulates glucose uptake into adipocytes, increases thermogenesis, energy expenditure, fat utilization, and improves glucose and lipid metabolism, and the pharmacological benefits of FGF21 in obesity-related metabolic complications, including cardiovascular disorders, has been a hot topic." (PMID 35145478, 2021). "Studies have found that FGF21 is nearly negatively related to obesity." (PMID 33869312, 2021). "FGF21 expression is regulated by a variety of nutrient stresses, such as starvation, a ketogenic diet, amino acid deprivation, undernutrition or malnutrition, and a high-fat diet or obesity." (PMID 34073755, 2021). "Interestingly, FGF21-mediated iWAT browning appeared to protect UCP1 KO mice housed at room temperature from diet-induced obesity." (PMID 34192547, 2021). "As FGF‐21 may be elevated in obesity, nutrition and body mass index could be potential confounding factors that may affect the metabolic status and hence the FGF‐21 levels." (PMID 34379890, 2021). "Therefore, the aim of this study is to shed light on the effects of two genes, previously reported to be associated with obesity (FTO and FGF21), on dietary patterns." (PMID 34095191, 2021). "Moreover, FGF21 can act on cardiac muscle to protect against heart disease and ameliorates obesity-related inflammation in a rat model reducing inflammatory cytokine production." (PMID 34046014, 2021). "Unlike other models of monogenic or diet-induced obesity and our previous results, exogenous FGF21 did not cause weight loss in Ay mice of both sexes." (PMID 34943946, 2021). "As a result, FGF21 is currently considered a potential target for the treatment of obesity." (PMID 33869312, 2021). "In summary, our study provides novel findings that may promote further work towards better understanding of the role of FGF21 in regulation of behavioral and metabolic traits related to obesity." (PMID 33805553, 2021). "We hypothesised that epigenetics may play an important role in mediating fibroblast growth factor 21 (FGF21) resistance in obesity." (PMID 33670024, 2021). "Fibroblast growth factor 21 (FGF21) is a classic metabolic regulator that plays a critical role in glucose and lipid metabolism through fibroblast growth factor signaling in patients with obesity and animal studies." (PMID 35002679, 2021). "In our study, we determined the Irisin and FGF-21 concentrations in children and adolescents with overweight and obesity before and one year after the implementation of a personalized, comprehensive, and multi-disciplinary life-style intervention program of diet and physical exercise." (PMID 33924457, 2021). "Thus, inhibition of FAP is thought to be a potential approach to increase endogenous FGF21 activity for the treatment of obesity and T2DM." (PMID 34572066, 2021). "Fibroblast growth factor 21 (FGF21) is a metabolic hormone produced by the adipose tissue, liver, skeletal muscle and pancreas, and it is reported that its serum concentrations are higher under conditions of insulin resistance and obesity." (PMID 34658643, 2021). "Akin to leptin resistance in obesity, increased FGF21 and GDF15 levels in obesity might indicate resistance to these cytokines, and a concomitant decrease in function, though this remains unresolved." (PMID 34777390, 2021).
Obesity (continued). "This suggests that DNA methylation and miRNAs analysis in leukocytes may reflect epigenetic changes in other tissues (liver, muscles, adipose tissue and bones) relevant for the pathogenesis of glucose and lipid disturbances related to high FGF21 in obesity." (PMID 33670024, 2021). "Moreover, several studies have shown convincing correlations between adipose FGF21 mRNA expression and circulating FGF21 levels in both humans and rodent models of obesity." (PMID 35046901, 2021). "Additionally, further research of FGF21 in brain tissue and meta-analysis of both human and mice studies would provide essential insights into FGF21 interaction as a predictor or biomarker for impaired obesity-related behavioural dysfunction." (PMID 34578793, 2021). "Because dysfunctional adipocytes are also observed in the obese state, it is therefore plausible that Ad-FGF21 could contribute to the elevated circulating FGF21 observed in models of obesity." (PMID 35046901, 2021). "In particular, the possibility that actions of adiponectin and Fgf21, both of which have therapeutic potential against obesity, under the physiological control of endogenous 5HT tone may be important from a clinical perspective." (PMID 34065591, 2021). "Indeed, overexpression of CREBH either genetically or by infection with CREBH adenovirus protected mice from diet-induced obesity through Fgf21-dependent mechanisms." (PMID 34023388, 2021). "Paradoxically metabolic disorders like obesity, diabetes are characterised by elevated serum FGF21." (PMID 33670024, 2021). "Collectively, these data highlight the ambiguity over the concept that obesity is an FGF21-resistant state, and suggest that there may be as yet unknown pathways by which adipocytes respond to FGF21." (PMID 35046901, 2021). "Importantly, these dysfunctional adipocytes were found to contribute to circulating FGF21 levels, reaching concentrations consistent with what has been observed in mouse models of obesity." (PMID 35046901, 2021). "Exciting recent studies implicate FGF21 in obesity-promoted PDAC." (PMID 34680216, 2021). "However, in obesity the state of FGF21 resistance is widely observed, which is suggested as compensatory up-regulation response to chronically elevated serum levels of FGF21." (PMID 33670024, 2021). "Due to its association with obesity and non-alcoholic fatty liver disease, the metabolic effects of endogenously produced FGF21 during the pathogenesis of these conditions are not well known." (PMID 35046901, 2021). "However, a growing body of evidence indicates a positive relationship between an increase in the serum levels of FGF-21 and obesity, dyslipidemia, insulin resistance, and DM." (PMID 33810243, 2021). "Indeed, elevated levels of FGF21 have been observed in patients with obesity and T2DM relative to lean subjects." (PMID 34572066, 2021). "In addition, FGF-21 is higher in children with obesity compared to those with normal BMI, and in children with metabolic syndrome or with diabetes mellitus type 2." (PMID 33924457, 2021). "Previously, we showed that the upregulation of Fgf21 expression in the liver was biased differently depending on sex and metabolic situation: toward females during adaptation to fasting, but toward males during adaptation to diet-induced obesity." (PMID 34638898, 2021). "Collectively, these data suggest that FGF21 levels rise during obesity in humans, and could derive from adipose tissue." (PMID 35046901, 2021). "FGF21 is a promising candidate for treating obesity, diabetes, and NAFLD; however, some of its pharmacological effects are sex-specific in mice with the Ay mutation that evokes melanocortin receptor 4 blockade, obesity, and hepatosteatosis." (PMID 34943946, 2021). "FGF21 was previously shown to suppress weight gain in animal models of obesity." (PMID 34074713, 2021).